ETV6 (ETS variant transcription factor 6)
Diseases named in the same sentence as ETV6 in open-access papers (continued):
Sharing a sentence is not in itself a finding about the gene and the disease.
leukemia (continued). "Our investigation of the TF pair FOXO1:ETV6 and its cooperativity-driven association with clinical features in CLL exemplifies this clearly and is reinforced by the observation of a FOXO1:ETV6 gene fusion in leukemia patients." (PMID 31913281, 2020). "An indirect pathway of MYC activation in ETV6/RUNX1-rearranged leukemia is mediated by the GTP-binding protein RAC1, a pivotal modulator of hematopoiesis, that increases the phosphorylation levels of STAT3." (PMID 32102485, 2020). "ETV6 inactivation likely represents part of the mechanism leading to the development of leukaemia and defining its features." (PMID 31845480, 2020). "We and others independently identified the ETS transcription factor ETV7, which is highly homologous to ETV6/TEL, a frequent target of chromosomal translocation in human leukemia." (PMID 30478527, 2019). "Gene expression analysis of mouse models and primary human leukemia suggested that reduced function of PAX5 increased the ability of an oncogenic form of IKZF1 or ETV6-AML to modulate gene expression." (PMID 31381561, 2019). "Gene ETV6 is relevant to multiple cancer types, including breast cancer, leukemia, non-small cell lung cancer, and others." (PMID 31405076, 2019). "ETV6, a member of the ETS family, is a transcriptional repressor required for bone marrow hematopoiesis and associated with leukemia development." (PMID 31001412, 2018). "This gene is expressed in both normal and tumor cells, and is involved in the translocation of the ETV6 gene in leukemia." (PMID 29875348, 2018). "An earlier study showed that the genomic locus containing ETV6 is the most common translocation site in leukemia." (PMID 29455655, 2018). "Relapsed childhood ETV6/RUNX1-positive leukemia is a clinically and biologically heterogeneous disease." (PMID 28418909, 2017). "Mutations in several other germ line leukemia predisposition genes (CEBPA, GATA2, ETV6) were also rare or undetected." (PMID 29326930, 2017). "Of note, mutations in several of the genes that confer leukemia predisposition (e.g., CEBPA, ETV6, GATA2, NF1, RUNX1, PTPN11, CBL, and RAS) are also frequently found in sporadic acute myeloid leukemia (AML) or myelodysplastic syndrome (MDS)." (PMID 29326930, 2017). "Additional, we also found another novel target (i.e., ETV6), alteration of which is frequently observed in leukemia in germline or somatic level." (PMID 28415601, 2017). "Deregulated expression of BCL2 family members has been described in the context of ETV6/RUNX1 positive leukemia." (PMID 26919255, 2016). "Loss of BCL2 modifying factor (BMF), a proapoptotic member of the BCL2 family, was recently shown in a single nucleotide polymorphism (SNP) array study to play a role in the development and relapse of ETV6/RUNX1 positive leukemia." (PMID 26919255, 2016). "First, we used primary leukemia patient samples to identify an ETV6/RUNX1 specific expression signature consisting of 596 lncRNA transcripts." (PMID 27650541, 2016). "In conclusion, we identify germline mutations in the gene encoding the critical hematopoietic transcription factor ETV6 that co-segregate with ALL and thrombocytopenia in a rare leukemia-prone kindred." (PMID 26522332, 2015). "The decreased expression of miR-181a-1 in ETV6/RUNX1-positive leukemias was validated in another cohort of pre-B ALL cases analyzed by real-time qRT-PCR." (PMID 26580398, 2015). "In conclusion, our study enhances the understanding of the molecular mechanism underlying ETV6/RUNX1-mediated attenuation of B-cell differentiation and offers the opportunity to identify new targets for development of therapeutic approaches to leukemia." (PMID 26580398, 2015). "Translocations involving the ETV6 locus (12p13) are a frequent event in leukemia and myelodysplastic syndrome." (PMID 24886876, 2014).
leukemia (continued). "Disruption of autoinhibition, such as by translocation of Abl1 or Abl2 next to a variety of different genes (e.g. Bcr, Tel, ETV6), leads to constitutive activation, which drives malignancies, particularly leukemias." (PMID 24223753, 2013). "We then searched for the biological pathways associated with genes differentially expressed in TEL/AML1-positive leukemia (ETV6/RUNX1)." (PMID 17956600, 2007). "Moreover, whole transcriptome data of 1,727 leukemia patient samples showed significantly elevated H1‐0 levels in ETV6::RUNX1+ BCP‐ALL compared to other leukemia entities." (PMID 40177616, 2025). "Notably, ETV6::RUNX1+ BCP‐ALL showed significantly elevated H1‐0 levels compared to other leukemia entities." (PMID 40177616, 2025). "Prenatal exposure to corticosteroids within a critical time window may therefore increase the risk of developing ETV6::RUNX1+ preleukemic clones and potentially leukemia after birth." (PMID 40243620, 2025). "In addition to focal deletions, gains of chromosome arms and extra chromosomes are also recurrently observed in ETV6::RUNX1 leukemia, with an average of four copy number variations (CNVs) per case." (PMID 40634509, 2025). "Similar pathogenic fusion genes are found in leukemias, such as AML1 (acute myeloid leukemia-1)-ETO (eight twenty-one), PML (promyelocytic leukemia)-RARα (retinoic acid receptor alpha), and ETV6 (ETS variant transcription factor 6)-RUNX1 (RUNX family transcription factor 1)." (PMID 40584293, 2025). "Moreover, a recent study found that when only “clustered” cases of leukemia are considered (those most likely to have been initiated by an infectious agent) the frequency of the ETV6/RUNX1 translocation rises to 40%." (PMID 41497616, 2025). "Most frequently, ETV6::RUNX1+ B-ALL harbors deletions of the second, non-translocated ETV6 allele, implying that the initial gene fusion predisposes individuals to leukemia, while subsequent ETV6 deletion acts as a promoting factor." (PMID 40243620, 2025). "It has been shown that EVI1 gene overexpression can induce leukemia in mice, so it is speculated that the promoter of ETV6 gene is working, making the EVIl gene overexpression." (PMID 39634885, 2024). "Moreover, studies in mice have revealed that the E::R fusion gene, when expressed under the control of the endogenous Etv6 promoter, induces leukemia at a notably low frequency." (PMID 38136366, 2023). "Using MI-FISH, we showed that the initiating ETV6::RUNX1 gene fusion was present in the PB of both twins but only cells from the twin with ALL had the additional multiple “drivers” of leukaemia - including deletion of the normal copy of ETV6, deletion of PAX5 and 10p gain." (PMID 36536099, 2023). "Loss of Kdm5c may be involved in the leukemogenesis of ETV6/RUNX1+ ALL, but it is doubtful whether it is a main second hit driving leukemia, as in humans it has been only observed in a relapse sample." (PMID 34336858, 2021). "Moreover, this subset also shares leukemia and pro‐B gene expression signatures as well as high levels of the ETV6 target genes (BIRC7, WBP1L, CLIC5, ANGPTL2) with the ER subtype, indicating that these B‐other cases are the recently identified ER‐like subtype." (PMID 33987955, 2021). "Studies in leukemia also indicate that an ETV6-FRK chimera could function as an oncogene contributing to leukemogenesis." (PMID 32082487, 2020). "Finally, we also observed that mRNA and proteins that were differentially expressed between hyperdiploid and ETV6/RUNX1-positive leukemia had higher mRNA-protein correlations." (PMID 30944321, 2019). "The model described here can act as a useful tool in this endeavour and could be relevant to study other common leukaemia-initiating events, such as ETV6/RUNX1 and MLL fusion events." (PMID 30867444, 2019).
leukemia (continued). "We found that a significantly higher proportion of the genes that were differentially expressed between high hyperdiploid and ETV6/RUNX1-positive leukemias were anchor genes in both the oligo(dT) and the RiboZero RNA-seq datasets (hypergeometric test; P = 0.0139 and P = 0.00513, respectively)." (PMID 30944321, 2019). "Here, the authors perform proteogenomic and Hi-C analyses of this leukemia and the ETV6/RUNX1 subtype and show that CTCF and cohesin expression are low in hyperdiploid cases and transcriptional dysregulation in relation to topologically associating domain borders in some of these cases." (PMID 30944321, 2019). "For ETV6, expression of this gene is positively associated with GATA3 in B-ALL only, and with the opposite direction in all other types of leukemia, breast cancer as well as the healthy bone marrow, indicating its specific role on B-ALL leukemogenesis with GATA3 regulation." (PMID 28415601, 2017). "IgH, TCR and ETV6/RUNX1 are leukemia-specific molecular markers in E/R-positive ALL." (PMID 28418909, 2017). "Initially, most studies addressing secondary leukemia-promoting genetic changes have focused on the deletion of the normal, or non-rearranged, ETV6 allele." (PMID 28418909, 2017). "Given the predicted link between these lncRNAs and resistance to vincristine, we examined whether these lncRNAs are able to identify a more aggressive subtype of ETV6/RUNX1-derived leukemia." (PMID 27650541, 2016). "Interestingly, 16 out of 50 lncRNAs overlapped with the ETV6/RUNX1-specific lncRNA signature that was identified in the primary leukemia samples, including 14 up- and 2 down-regulated lncRNA transcripts." (PMID 27650541, 2016). "Furthermore, we also identified a strong correlation in ETV6/RUNX1-positive leukemias between NETO1 and its adjacent, bidirectional lncRNA lnc-TIMM21-5 (r = 0.89) as well as between LRP8 and lnc-CPT2-7 (r = 0.70)." (PMID 27650541, 2016). "E/Rtg mice were bred with Vav-BCL2 transgenic mice to assess whether the antiapoptotic protein BCL2 would cooperate with ETV6/RUNX1 to initiate leukemia." (PMID 26919255, 2016). "Evidence would suggest that the HLXB9/ETV6 positive leukaemias might be initiated through an alterations of interactions between the HSC and the HSC niche." (PMID 26605042, 2015). "We also found important differences between the two subtypes of leukemic cells, with Leukemia 1 cells overexpressing a number of important leukemia regulators, including Etv6 and Runx1, providing support that these cells are more important for tumor initiation." (PMID 25517911, 2014). "Notably, the amplification of ETV6 has been identified as a potential oncogene of leukemia." (PMID 37483430, 2023). "Indeed, previous literature on the distribution of cytogenetic abnormalities among ALL patients of varying racial and ethnic groups has suggested that ETV6/RUNX1 leukemia is less common in Hispanics and East Asian populations compared with populations of European ancestry." (PMID 33968846, 2021). "Taking these differences into account, we still noted that several genes were missing in the PanelApp panels which most likely would fulfill their criteria, for instance the leukemia predisposing genes ETV6 and RUNX1 (not mentioned) and the hereditary paraganglioma gene SDHB (marked red)." (PMID 34061292, 2021). "ETV6 belongs to the ETS family of transcription factors and has been found to have at least 20 different gene fusion partners and is also found to have other genetic alterations including deletions, point mutations, and promoter alterations in various leukemias." (PMID 24847444, 2014).
leukemia (continued). "Functional investigations of ETV6 variants have shown that they are associated with disrupted expression of genes involved in platelet production and platelet cytoskeleton dynamics, including the CDC42 and RHOA218 genes, but the mechanisms driving leukemia remain unclear." (PMID 40008001, 2025). "In this study, we performed proteomic and phosphoproteomic profiling of samples collected at diagnosis and remission from pediatric leukemia patients with one of two subtypes of B-ALL: BCR::ABL1-like (Ph-like) and ETV6::RUNX1." (PMID 40832224, 2025). "Modeling approaches of ETV6::RUNX1+ preleukemia and overt leukemia in mice were largely unable to reproduce restriction to B lineage leukemia seen in humans." (PMID 40177616, 2025). "To extend these approaches to pediatric leukemias, we profile samples from patients diagnosed with one of two well-defined subtypes: BCR::ABL1-like and ETV6::RUNX1 B-ALL, which have distinct prognoses, known signaling pathways, and treatment approaches." (PMID 40832224, 2025). "Taken together, these data add to our understanding of the molecular profile of Ph-like and ETV6::RUNX1 B-ALL, demonstrating the utility of multi-omic comparison in pediatric leukemia subtype characterization." (PMID 40832224, 2025). "The ETV6::RUNX1 fusion acts as a weak oncogene and is insufficient to initiate leukemia independently." (PMID 40634509, 2025). "Leukemia is estimated to occur in about 30% of carriers, most commonly in ALL, but more than 30 translocation partners of ETV6 have been reported in AML, MDS, MPN, and T-cell lymphomas." (PMID 38203823, 2024). "It is interesting that both the patients with LMNB1::PPP2R2B fusion carried ETV6::RUNX1 fusion, implying that LMNB1::PPP2R2B fusion played a role in the pathogenesis of ETV6::RUNX1-positive leukemia." (PMID 36612032, 2022). "The first is that the relative frequency of childhood ALL, and ETV6/RUNX1 ALL in particular, compared with childhood AML has led to more investigation of this leukemia subtype." (PMID 33968846, 2021). "The ETS transcription factor TEL/ETV6, a frequent target of chromosomal translocation in human leukemia, is known to be a selective and essential regulator of HSC survival in mice." (PMID 30478527, 2019). "This new category is characterized by ETV6 and IKZF1 aberrations and by the same gene-expression profile as ETV6-RUNX1 positive leukaemia." (PMID 31208040, 2019). "Other transcriptional targets of ETV6 include SPHK1, PTGER4 and CLIC5, which can promote survival and proliferation of leukaemia cell lines." (PMID 28819864, 2018). "Pediatric ETV6/RUNX1-positive leukemia generally has favorable long-term remission and survival rates, but as in ALL initial manifestation, ETV6/RUNX1 is the most common structural genetic aberration in childhood B-cell precursor (BCP) ALL at first relapse." (PMID 28418909, 2017). "A previous study by Fernando and colleagues also evaluated lncRNA expression signatures in genetic subtypes of human BCP-ALL using 14 ETV6/RUNX1, 15 TCF3/PBX1 and 15 MLL-rearranged leukemia specimens." (PMID 27650541, 2016). "However, although a possible link between a genetic predisposition factor in the pathogenesis of autoimmunity and leukemogenesis has been recently proposed, we are not aware of any case reports for ETV6/RUNX1+ leukemia patients associated with autoimmune disease (and/or glomerulonephritis)." (PMID 26919255, 2016). "The authors postulate that deletions of the following genes ETV6, VPREB1, CDKN2A/B, TBL1XR1, PAX5 as well as BTLA and CD200 are very early and essential events in leukemia development." (PMID 27933341, 2016). "Thus, placing the ETV6/RUNX1 transgene under control of the Cd19 promoter may be too late to allow for B cell progenitor leukemia development when combined with BCL2 overexpression, but still allowing to promote autoimmune mature B cell abnormalities that aggravate glomerulonephritis." (PMID 26919255, 2016).
leukemia (continued). "All together, our study defined a unique lncRNA expression signature associated with ETV6/RUNX1-positive BCP-ALL and identified lnc-RTN4R-1 and lnc-NKX2-3-1 as lncRNAs that might be functionally implicated in the biology of this prevalent subtype of human leukemia." (PMID 27650541, 2016). "Here, we provide a comprehensive overview of lncRNA expression in ETV6/RUNX1-positive BCP-ALL and analyze the transcriptional consequences of lncRNA modulation in the context of ETV6/RUNX1 rearranged leukemia." (PMID 27650541, 2016). "Here, we conducted a comprehensive analysis of the long non-coding RNA transcriptome in ETV6/RUNX1-positive BCP-ALL, one of the most frequent subtypes of pediatric leukemia." (PMID 27650541, 2016). "This included two leukemia cell lines, RCH-ACV and REH, known to carry the TCF3:PBX1 and ETV6:RUNX1 fusion genes, respectively, and four prostate cancer samples positive for the TMPRSS2:ERG fusion gene." (PMID 19152679, 2009). "Using this array, proof of principle was demonstrated by detection of known fusion genes (such as TCF3:PBX1, ETV6:RUNX1, and TMPRSS2:ERG) from all six positive controls consisting of leukemia cell lines and prostate cancer biopsies." (PMID 19152679, 2009). "Similar studies of umbilical cord blood samples have shown that the frequencies of ETV6/RUNX1 and RUNX1/ETO, for example, are 100 times higher in neonates than in pediatric leukemia patients." (PMID 21637673, 2009). "A genetic analysis of random cord blood samples found the ETV6/RUNX1 translocation in 1%, a frequency 100-fold greater than the frequency of overt leukemia with that fusion gene in the population at large, indicating that 99% of the time these expanded clones fail to develop into leukemia." (PMID 41497616, 2025). "However, ETV6::RUNX1, TCF3::PBX1, and T‐ALL had low MTXPG intracellular accumulation in leukemia cells." (PMID 39485718, 2024). "ETV6::RUNX1 is known to be a weak oncogene unable to induce leukemia in the absence of secondary genetic alterations." (PMID 37670323, 2023). "The incidence of detectable pre-leukemia in asymptomatic children is many times that of the incidence of overt childhood BCP-ALL; for example, ETV6::RUNX1+ pre-leukemia is approximately 100-500x more common than ETV6::RUNX1+ BCP-ALL." (PMID 36959797, 2023). "We showed that the SV landscapes in ETV6::RUNX1 and classical HD leukemia are profoundly different." (PMID 37469802, 2023). "We developed a zebrafish model for E::R leukemia using CRISPR/Cas9 to introduce the human RUNX1 gene into zebrafish etv6 intron 5, resulting in E::R fusion gene expression controlled by the endogenous etv6 promoter." (PMID 38136366, 2023). "Additionally, the ETV6/RUNX1 fusion gene can be stabilized at the mRNA level by the RNA-binding protein IGF2BP1, which is overexpressed in this type of leukemia." (PMID 32102485, 2020). "The disrupted products of the fusion between the ETV6 and RUNX1 transcription factors, involved in B cell maturation, could result in an overall lower maturation potential of the leukemia cells." (PMID 32415257, 2020). "A specific leukemia where cut-and-run could play a significant role is ALL where patients bear the ETV6/RUNX1 (TEL/AML1) translocation." (PMID 30905508, 2019). "Most of these molecular changes are acquired, not inherited, as only a small number of leukaemias are associated with inherited genetic syndromes as is the case for germline mutations in PAX5, ETV6 or IKZF1." (PMID 31380372, 2019). "Presence of ETV6/RUNX1 alone is usually not sufficient for leukemia onset, and additional genetic alterations have to occur in ETV6/RUNX1-positive cells to cause transformation." (PMID 26919255, 2016). "Furthermore, cryptic genomic alterations involving leukemia-related genes, such as ATP2B2, ANGPT1, ETV6 and RB1CC1, were inferred in the level of array CGH and confirmed by FISH." (PMID 25120648, 2014).